PAXIP1 (PAX interacting protein 1)
Description:
Involved in DNA damage response and in transcriptional regulation through histone methyltransferase (HMT) complexes. Plays a role in early development. In DNA damage response is required for cell survival after ionizing radiation. In vitro shown to be involved in the homologous recombination mechanism for the repair of double-strand breaks (DSBs). Its localization to DNA damage foci requires RNF8 and UBE2N. Recruits TP53BP1 to DNA damage foci and, at least in particular repair processes, effective DNA damage response appears to require the association with TP53BP1 phosphorylated by ATM at 'Ser-25'. Together with TP53BP1 regulates ATM association. Proposed to recruit PAGR1 to sites of DNA damage and the PAGR1:PAXIP1 complex is required for cell survival in response to DNA damage; the function is probably independent of MLL-containing histone methyltransferase (HMT) complexes. However, this function has been questioned (By similarity). Promotes ubiquitination of PCNA following UV irradiation and may regulate recruitment of polymerase eta and RAD51 to chromatin after DNA damage. Proposed to be involved in transcriptional regulation by linking MLL-containing histone methyltransferase (HMT) complexes to gene promoters by interacting with promoter-bound transcription factors such as PAX2. Associates with gene promoters that are known to be regulated by KMT2D/MLL2. During immunoglobulin class switching in activated B-cells is involved in trimethylation of histone H3 at 'Lys-4' and in transcription initiation of downstream switch regions at the immunoglobulin heavy-chain (Igh) locus; this function appears to involve the recruitment of MLL-containing HMT complexes. Conflictingly, its function in transcriptional regulation during immunoglobulin class switching is reported to be independent of the MLL2/MLL3 complex (By similarity).
Synonyms: PAXIP1L; PTIP; CAGF28; CAGF29; TNRC2; PACIP1
Tractability: PROTAC: ubiquitination databases record sites on it; its protein half-life has been measured.
Gene: Protein-coding gene on chromosome 7 (154,943,687 to 155,003,124, reverse strand). Ensembl gene ENSG00000157212.
Subcellular location: Nucleus matrix; Chromosome
Subcellular location (Human Protein Atlas): Nucleoplasm; Vesicles
Pathways (Reactome):
Gene expression (Transcription): Epigenetic regulation of gene expression by MLL3 and MLL4 complexes; Formation of WDR5-containing histone-modifying complexes; MLL4 and MLL3 complexes regulate expression of PPARG target genes in adipogenesis and hepatic steatosis
DNA Repair: Nonhomologous End-Joining (NHEJ)
Developmental Biology: Activation of anterior HOX genes in hindbrain development during early embryogenesis
Gene Ontology:
Molecular function: protein binding
Biological process: chromatin remodeling; positive regulation of transcription initiation by RNA polymerase II; response to ionizing radiation; positive regulation of isotype switching; positive regulation of protein ubiquitination; adipose tissue development; chorion development; DNA damage response; endothelial cell migration; positive regulation of isotype switching to IgG isotypes; regulation of cell cycle G2/M phase transition; vasculogenesis
Cellular component: chromosome; histone methyltransferase complex; MLL3/4 complex; nucleus; nucleoplasm; nuclear matrix
Genetic constraint (gnomAD): Loss-of-function variants: 10 observed, 61.59 expected, observed/expected ratio (o/e) 0.16, 90% interval 0.099 to 0.28. The upper end of that interval is the gene's LOEUF score, 0.28, which puts it in group 1 of 6, group 1 being the genes least tolerant of losing a copy. Missense variants: 547 observed, 759.06 expected, observed/expected ratio (o/e) 0.72, 90% interval 0.67 to 0.77. Synonymous variants: 274 observed, 279.22 expected, observed/expected ratio (o/e) 0.98, 90% interval 0.89 to 1.09.
Homologues: Orthologues: chimpanzee PAXIP1 (99% identical), macaque PAXIP1 (99% identical), rabbit PAXIP1 (90% identical), dog PAXIP1 (88% identical), rat Paxip1 (86% identical), mouse Paxip1 (86% identical), guinea pig PAXIP1 (84% identical), pig PAXIP1 (83% identical), tropical clawed frog paxip1 (77% identical), zebrafish paxip1 (66% identical), Caenorhabditis elegans pis-1 (22% identical). Paralogues in human: MDC1 (19% identical).
Diseases named in the same sentence as PAXIP1 in open-access papers:
PAXIP1 is named in the same sentence as 29 diseases in open-access papers, as found by Europe PMC text mining. Sharing a sentence is not in itself a finding about the gene and the disease. The quoted sentences say what the papers report.
breast carcinoma (9 papers, 2015 to 2025). "Somatic copy number variation (CNV) of PAXIP1 has also been associated with breast cancer prognosis." (PMID 34274969, 2021). "Similar to our findings, lower expression of PAXIP1 in breast cancer was associated with poorer prognosis." (PMID 31332257, 2019). "lncRNA PAXIP1 has been noted to correlate with breast cancer staging and survival, suggesting its prognostic significance in cancer." (PMID 31823805, 2019). "Moreover, NOP14 is one of the proteins that interact with PAXIP1, which contains tandem breast cancer carboxy-terminal domains and regulates multiple aspects of the cellular response to DNA damage, such as cell survival and differentiation." (PMID 26213846, 2015). "The PAX interacting protein 1 (PAXIP1) contributes to DNA repair and correlates with breast cancer staging." (PMID 36458022, 2022).
ovarian carcinoma (5 papers, 2013 to 2023). A malignant neoplasm originating from the surface ovarian epithelium. "Consistently, BRCA2 mutated ovarian cancers with reduced PAXIP1 or CHD4 expression are associated with shorter progression-free survival and shorter overall survival." (PMID 34645978, 2021).
glioma (3 papers, 2021 to 2022). A benign or malignant brain and spinal cord tumor that arises from glial cells (astrocytes, oligodendrocytes, ependymal cells). "PAXIP1.AS2 has been reported as ferroptosis-associated lncRNA that could affect the radiotherapy response for glioma." (PMID 36033510, 2022). "The forest plot shows that EPB41L4A.AS1, GDNF.AS1, HAR1A, LINC00237, SLC25A21.AS1, SNA13.AS1, and WDFY3.AS2 are the protective factors with HR < 1, while LINC00092, LINC00265, LINC00339, LINC00665, PAXIP1.AS2, SNHG16, SNHG9 and SOCS2.AS1 are risk factors with HR>1 in glioma patients." (PMID 35273128, 2022).
myeloma (2 papers, 2022 to 2023). "In addition, MDH2, MPC2, PAXIP1, and NSDHL were upregulated in myeloma patients." (PMID 37333985, 2023).
Atrophy (1 paper, 2020). Any weakening or degeneration, especially through lack of use. "Finally, PAXIP1 is critical for genome stability and chromatin condensation and is associated with developmental arrest of spermatocytes, testicular atrophy and infertility in knockout mice." (PMID 32409652, 2020).
leukemia (1 paper, 2020). A malignant (clonal) hematologic disorder, involving hematopoietic stem cells and characterized by the presence of primitive or atypical myeloid or lymphoid cells in the bone marrow and the blood. "Downregulation of PAXIP1 has also been associated with downregulation of leukemia cells." (PMID 33195511, 2020). "The role of blv-miR-B1-5p in the regulation of PAXIP1 is unclear given that downregulation of PAXIP1 would result in a downregulation of leukemia cells." (PMID 33195511, 2020).
skin cancer (1 paper, 2022). "In skin cancer, PAXIP1, EXO1, and RIF1 associated with dHRVAE1, the component correlating with SNV signature 3 mutations." (PMID 35764656, 2022).
viral infections (1 paper, 2020). "We confirmed variants with putative driver role of MAP10, MPZL1, RPS6KA1, SETD1B, TAOK2, TMEM127, and TNFRSF1A genes, and of genes linked to viral infections (DDX3X and RSF1) and DNA repair (PAXIP1)." (PMID 32321919, 2020).
cancer (13 papers, 2013 to 2024). A tumor composed of atypical neoplastic, often pleomorphic cells that invade other tissues. "Filtering the data with a less stringent minor allele frequency (MAF) threshold (MAF < 0.001) identified variants in eight additional candidate genes, of which one (PAXIP1) is a genome stability gene previously associated with cancer." (PMID 34274969, 2021). "As expected, genes including 53BP1 and PAXIP1 previously identified in murine models as synthetically viable in BRCA1/BRCA2-deficient tumors were not frequently altered in human cancers." (PMID 39198848, 2024). "We chose to focus on STAG2 because of its importance as a tumor-suppressor gene lost in various cancers, PAXIP1 a recently identified cohesin regulator, and the Haspin kinase since it may be targetable with small molecules." (PMID 38478595, 2024). "Others have cancer-relevant functions, such as steroid hormone synthesis (HSD17B8, earlier), and covalent modification of histones (HUWE1, IPO7, MLL4, PAXIP1, PRKAA2, all later except PAXIP1)." (PMID 23762276, 2013). "KHDRBS1 showed a larger difference in expression level when compared to PAXIP1, although differences for both genes were not statistically significant, likely due to the low number of BRCA2 mutant cancers." (PMID 30626869, 2019).
tumor (4 papers, 2011 to 2018). "The PAXIP1 L537F mutation was subclonal in the primary tumor and expanded to become clonal in the brain metastases." (PMID 29755676, 2018). "Further examples for a heterozygous status in the leukocytes as compared to a hemizygous or homozygous in the according tumor were found for the SNP rs1805414 mapping in PARP1 gene, SNP rs935037 in PAXIP1 gene and SNP rs962976 in MDM1 gene." (PMID 21695249, 2011).
infection (1 paper, 2025). The state of being infected such as from the introduction of a foreign agent such as serum, vaccine, antigenic substance or organism. "Notably, genes such as Cyp26b1, Dbp, Kcng1, Cdca7l, Paxip1, Stxbp2 and Gpi1 were also observed to be significantly up-regulated (p<0.05) in the hMHC mice on various days post-infection." (PMID 40822594, 2025).
PAXIP1 also shares sentences with these, for which no sentence is quoted: cardiac disease (1 paper); cardiac hypertrophy (1); Cornelia de Lange syndrome (1); endometrial cancer (1); esophageal squamous cell carcinoma (1); Glomerular sclerosis (1); heart failure (1); hepatocellular carcinoma (1); Infertility (1); liver cancer (1); liver cirrhosis (1); lung carcinoma (1); microphthalmia (1); oligodendroglial tumours (1); renal disease (1); Thyroid Carcinoma (1); triple-negative breast carcinoma (1); uterine corpus endometrial carcinoma (1).